AP2A2 (adaptor related protein complex 2 subunit alpha 2)
Description:
Component of the adaptor protein complex 2 (AP-2). Adaptor protein complexes function in protein transport via transport vesicles in different membrane traffic pathways. Adaptor protein complexes are vesicle coat components and appear to be involved in cargo selection and vesicle formation. AP-2 is involved in clathrin-dependent endocytosis in which cargo proteins are incorporated into vesicles surrounded by clathrin (clathrin-coated vesicles, CCVs) which are destined for fusion with the early endosome. The clathrin lattice serves as a mechanical scaffold but is itself unable to bind directly to membrane components. Clathrin-associated adaptor protein (AP) complexes which can bind directly to both the clathrin lattice and to the lipid and protein components of membranes are considered to be the major clathrin adaptors contributing the CCV formation. AP-2 also serves as a cargo receptor to selectively sort the membrane proteins involved in receptor-mediated endocytosis. AP-2 seems to play a role in the recycling of synaptic vesicle membranes from the presynaptic surface. AP-2 recognizes Y-X-X-[FILMV] (Y-X-X-Phi) and [ED]-X-X-X-L- [LI] endocytosis signal motifs within the cytosolic tails of transmembrane cargo molecules. AP-2 may also play a role in maintaining normal post-endocytic trafficking through the ARF6-regulated, non-clathrin pathway. During long-term potentiation in hippocampal neurons, AP-2 is responsible for the endocytosis of ADAM10. The AP-2 alpha subunit binds polyphosphoinositide-containing lipids, positioning AP-2 on the membrane. The AP-2 alpha subunit acts via its C-terminal appendage domain as a scaffolding platform for endocytic accessory proteins. The AP-2 alpha and AP-2 sigma subunits are thought to contribute to the recognition of the [ED]-X-X-X-L-[LI] motif (By similarity).
Synonyms: HIP-9; ADTAB; CLAPA2; HIP9; HYPJ; KIAA0899; DKFZP564D1864
Tractability: Antibody: its Gene Ontology location is reachable by antibodies, with high confidence; UniProt places it where antibodies can reach, with medium confidence. PROTAC: ubiquitination databases record sites on it; its protein half-life has been measured.
Gene: Protein-coding gene on chromosome 11 (924,881 to 1,012,245, forward strand). Ensembl gene ENSG00000183020.
Subcellular location: Cell membrane; Membrane, coated pit
Subcellular location (Human Protein Atlas): Vesicles; Nucleoplasm
Pathways (Reactome):
Disease: Dengue Virus Attachment and Entry; Nef Mediated CD4 Down-regulation; Nef Mediated CD8 Down-regulation; Potential therapeutics for SARS
Signal Transduction: Retrograde neurotrophin signalling; WNT5A-dependent internalization of FZD2, FZD5 and ROR2; WNT5A-dependent internalization of FZD4
Developmental Biology: EPH-ephrin mediated repulsion of cells; Recycling pathway of L1
Immune System: MHC class II antigen presentation; Neutrophil degranulation
Transport of small molecules: LDL clearance; VLDLR internalisation and degradation
Vesicle-mediated transport: Cargo recognition for clathrin-mediated endocytosis; Clathrin-mediated endocytosis
Neuronal System: Trafficking of GluR2-containing AMPA receptors
Gene Ontology:
Molecular function: clathrin adaptor activity; protein binding; protein kinase binding; disordered domain specific binding; kinase binding; protein domain specific binding
Biological process: clathrin-dependent endocytosis; postsynaptic neurotransmitter receptor internalization; vesicle-mediated transport; intracellular protein transport; protein transport; synaptic vesicle endocytosis
Cellular component: AP-2 adaptor complex; plasma membrane; clathrin-coated endocytic vesicle; clathrin-coated endocytic vesicle membrane; cytoplasmic side of plasma membrane; cytoplasmic vesicle; cytosol; endocytic vesicle membrane; endolysosome membrane; ficolin-1-rich granule membrane; secretory granule membrane; clathrin adaptor complex; membrane; membrane coat; postsynapse; presynapse
Genetic constraint (gnomAD): Loss-of-function variants: 28 observed, 87.9 expected, observed/expected ratio (o/e) 0.32, 90% interval 0.23 to 0.44. The upper end of that interval is the gene's LOEUF score, 0.44, which puts it in group 1 of 6, group 1 being the genes least tolerant of losing a copy. Missense variants: 884 observed, 1,171.2 expected, observed/expected ratio (o/e) 0.75, 90% interval 0.71 to 0.8. Synonymous variants: 531 observed, 496.35 expected, observed/expected ratio (o/e) 1.07, 90% interval 1 to 1.15.
Homologues: Orthologues: macaque AP2A2 (99% identical), mouse Ap2a2 (97% identical), rat Ap2a2 (97% identical), guinea pig AP2A2 (97% identical), dog AP2A2 (95% identical), pig AP2A2 (91% identical), Drosophila melanogaster AP-2alpha (69% identical), Caenorhabditis elegans apa-2 (65% identical). Paralogues in human: AP2A1 (83% identical), AP1G1 (24% identical), AP1G2 (23% identical), AP4E1 (22% identical).
Diseases named in the same sentence as AP2A2 in open-access papers:
AP2A2 is named in the same sentence as 29 diseases in open-access papers, as found by Europe PMC text mining. Sharing a sentence is not in itself a finding about the gene and the disease. The quoted sentences say what the papers report.
Alzheimer disease (6 papers, 2018 to 2024). A progressive, neurodegenerative disease characterized by loss of function and death of nerve cells in several areas of the brain leading to loss of cognitive function such as memory and language. "The AP2A2 gene, which has been associated with Alzheimer’s disease, is widely transcribed in human tissues, particularly the brain." (PMID 38724875, 2024). "Recently, an epidemiological study reported that two variants (rs7396366 and rs2526378) closest to the AP2A2 and BZRAP1 genes are associated with higher plasma lipids and Alzheimer’s disease." (PMID 30086706, 2018). "AP2A2 gene function may be related to several mechanisms including pathogenesis like Alzheimer's disease." (PMID 37639552, 2023). "Moreover, several studies reported the potential association between AP2A2 gene variants and asthma, wheeze in childhood and adolescence, and chronic bronchitis, and BZRAP1 variants and Alzheimer’s disease." (PMID 30086706, 2018). "Recently, an epidemiological study reported that two genetic variants of single nucleotide polymorphisms (SNPs), rs7396366, whose closest gene is AP2A2, and rs2526378, whose closest gene is BZRAP1, are associated with higher plasma lipids and Alzheimer’s disease." (PMID 30086706, 2018). "However, evidence of late-onset Alzheimer disease (LOAD)-associated genetic polymorphism within an exon of Mucin 6 (MUC6) and immediately downstream from the Adaptor Related Protein Complex 2 Subunit Alpha 2 (AP2A2) have been reported." (PMID 34976023, 2021). "A recent report indicates colocalization of AP2A1 with neurofibrillary tangles in AP2A1 and AP2A2 plasmid-transfected cultured cells, suggesting the involvement of AP2 proteins in etiology of late-onset Alzheimer’s disease." (PMID 38674386, 2024).
asthma (2 papers, 2017 to 2018). "In the EWAS of current asthma at 16.5 years, the two CpGs that remained significant after adjustment for detailed cells mapped to the AP2A2 and IL5RA genes." (PMID 29046734, 2017). "The CpGs mapped to the AP2A2 and IL5RA genes, with a − 2.32 [95% CI − 1.47, − 3.18] and − 2.49 [95% CI − 1.56, − 3.43] difference in percentage methylation in asthma cases respectively." (PMID 29046734, 2017).
epilepsy (2 papers, 2023). A brain disorder characterized by episodes of abnormally increased neuronal discharge resulting in transient episodes of sensory or motor neurological dysfunction, or psychic dysfunction. "Some of them were already known to play a role in AD: PICK1 is involved in synaptic scaling; AP2A2 is involved in receptor-mediated endocytosis; SYT7 is regulated by amyloid precursor protein; and KIF5B is critical for GABAAR transport, and its deletion causes epilepsy." (PMID 36538112, 2023).
ovarian carcinoma (2 papers, 2016 to 2021). A malignant neoplasm originating from the surface ovarian epithelium. "There were only 4 PPAR-TRGs (AP2A2, DOCK4, HSDL2, and PDK4) out of 269 DEGs, which are associated with platinum chemosensitivity in ovarian cancer." (PMID 33613670, 2021).
breast tumors (1 paper, 2022). "For example, events in CYB561 and CEACAM1 are enriched in HER2+, and E2F4, AP2A2, MGAT4B, and DUXAP9 events are enriched in basal-like breast tumors." (PMID 35044822, 2022).
bronchitis (1 paper, 2017). An acute or chronic inflammatory process affecting the bronchi. "Genetic polymorphisms of the AP2A2 gene have also previously found to be associated with bronchitis and chronic obstructive pulmonary disease (COPD)." (PMID 29046734, 2017).
dementia (1 paper, 2022). Loss of intellectual abilities interfering with an individual's social and occupational functions. "These loci are associated with several dementia-related genes, including PON1, AP2A2, MAGI2, POT1, ITGAX, PACSIN1, SLC2A8, and EIF4E." (PMID 35299244, 2022).
emphysema (1 paper, 2014). "Among COPD subjects with ≥10% emphysema, chromosome 11p15.5, which includes genes AP2A2, MUC6 and CHID1, was the most significant region (rs7483870, β = 0.16L, P = 3.93 × 10−7; rs4076950, β = 0.13L, P = 2.88 × 10−6; rs4963123, β = 0.13L, P =3.40 × 10−6)." (PMID 25134640, 2014).
frontotemporal lobar degeneration (1 paper, 2018). "Remarkably, a recent proteomic analysis identified dysfunction in cellular transport, energy, and protein metabolism in different brain regions of individuals with atypical frontotemporal lobar degeneration (FTLD) with fused in sarcoma inclusions (aFTLD-U) associated with AP2A2." (PMID 30425636, 2018).
lung carcinoma (1 paper, 2020). "Many new targets of IgGs in lung cancer were non-cell surface proteins, but we noticed that many targets of these IgGs were adaptor proteins, such as the AP-2 complex including AP2A1, AP2A2, AP2B1, AP2S1, and AP2M1." (PMID 32580738, 2020).
pancreatic cancer (1 paper, 2020). "Furthermore, based on data reported in the Human Protein Atlas database, AP2A2, PLST, PLSI, BLVRB and SLC2A1 were associated with poor 5-year overall survival in pancreatic cancer." (PMID 33048956, 2020).
papillary thyroid cancer (1 paper, 2024). "Stratification of papillary thyroid cancer (THCA) TCGA expression data using quartile values (Q3Q4 vs Q1Q2) further highlighted the potential clinical relevance for 5 of these NIS interactors (AP2A2, ARF6, CTTN, HLA-A and RAB5C) on disease recurrence following RAI treatment (P < 0.05)." (PMID 37921808, 2024).
Sleep apnea (1 paper, 2017). An intermittent cessation of airflow at the mouth and nose during sleep is known as sleep apnea. "Significant associations of symptoms of sleep apnea were observed with six rare variants [minor allele frequency (MAF) <1%] (located in ACE, AIFM3, LIPJ, MUC2, AP2A2, SH3BP1)." (PMID 29093733, 2017).
cancer (2 papers, 2019 to 2021). A tumor composed of atypical neoplastic, often pleomorphic cells that invade other tissues. "Both AP2A1 and AP2A2 were reported to confer resistance to erlotinib, an anti-cancer drug, in lung cancer cells; interact with Shc, an SH2-containing proto-oncogene involved in growth factor signaling in mammalian cancer cells; and function in hemopoietic stem cell development." (PMID 34565296, 2021). "Interestingly, unlike AP2A1, no reported correlation was found between AP2A2 and cancer." (PMID 34565296, 2021).
brain diseases (1 paper, 2015). "The three genes (AP2A2, CACNG2, and RAB3A) in gene sets of at least two brain diseases were significantly enriched 'synaptic transmission' term of Reactome pathway with Benjamini corrected p-value of 0.022." (PMID 26043779, 2015).
cardiac disease (1 paper, 2018). "All these data point to the possibility that AP2A2 plays a remarkable role in energy metabolism and lipid transport and is potentially associated with nerve and cardiac disease." (PMID 30086706, 2018).
infection (1 paper, 2025). The state of being infected such as from the introduction of a foreign agent such as serum, vaccine, antigenic substance or organism. "Moreover, RPS5, AHCYL1 and AP2A2, host factors with presumed proviral roles in IAV infection, were enriched upon infection in our system." (PMID 40623098, 2025).
AP2A2 also shares sentences with these, for which no sentence is quoted: breast carcinoma (2 papers); chronic bronchitis (1); chronic obstructive pulmonary disease (1); COVID-19 (1); depression (1); late-onset Alzheimers disease (1); neuroblastoma (1); neurological diseases (1); Parkinson’s (1); periodontitis (1); sarcoma (1); tumor (1).